GRB7 (growth factor receptor bound protein 7)
Diseases named in the same sentence as GRB7 in open-access papers (continued):
Sharing a sentence is not in itself a finding about the gene and the disease.
breast carcinoma (continued). "The effect of nonphosphorylated peptide 41 on the proliferation of SK-BR-3 breast cancer cells, which express high levels of the Grb7 protein, was evaluated using the MTS (3-(4,5-dimethylthiazol-2-yl)-5-(3-carboxymethoxyphenyl)-2-(4- sulfophenyl)-2H-tetrazolium, inner salt) cell proliferation assay." (PMID 22253820, 2012). "For example, evidence in breast cancer cell lines suggests that GRB7 may be involved in proliferation and that inhibiting both HER2 and GRB7 may enhance the inhibitory effect on cell growth." (PMID 22067903, 2011). "While the role of some amplicon genes may be less relevant for breast cancer development, the function of GRB7 is intriguing." (PMID 20459607, 2010). "Finally, we show that Grb7 removal by RNA-interference reduces breast cancer cell viability and increases the activity of lapatinib." (PMID 20126311, 2010). "It is conceivable that, in these conditions, Grb7 accumulation as a consequence of HER2 signaling inhibition may increase breast cancer cell aggressiveness and thereby speed up metastatic disease progression." (PMID 20126311, 2010). "GRB7 showed strong correlation between mRNA transcript levels and copy number status in this study, and increased mRNA expression has been shown to correlate with protein overexpression in breast cancer cell lines." (PMID 20459607, 2010). "However, the minimum region of recurrent amplification within the 17q12 amplicon includes just the STARD3, ERBB2 and GRB7 genes in human breast cancer." (PMID 19424485, 2008). "Moreover, Grb7 is co-expressed with ErbB3 and ErbB4, which are known to heterodimerise with ErbB2, in a subgroup of human breast cancer cell lines." (PMID 17426702, 2007). "Additionally, GRB7 shows promise as a potential therapeutic target in breast cancer as well." (PMID 39204147, 2024). "As with breast cancer, membrane expression of GRB7 protein is present in ovarian cancer samples with high GRB7 expression (3+) in the cytoplasm but only a fraction of ovarian cancer specimens with high cytoplasmic expression of GRB7 protein (3+) exhibit GRB7 membrane expression." (PMID 32595827, 2020). "Grb7 is a signaling adaptor protein that has been specifically targeted through the development of cyclic peptide inhibitors that are able to inhibit proliferation and migration in breast cancer cell lines and reduce tumor metastasis in a mouse model of pancreatic cancer." (PMID 29018805, 2017). "In conclusion, our work provides evidence that the GRB7 gene may be the focus of some cases of the chromosome 17q11-12 amplification and selective retention, further strengthening the prognostic importance of GRB7 protein over-expression in breast cancer." (PMID 24102037, 2013). "In addition, Grb7 upregulation was shown to confer resistance to hormone therapy in breast cancer." (PMID 20126311, 2010). "Migration and invasion enhancer I (MIEN1) and growth factor receptor-bound protein 7 (GRB7) are genes located proximal to the ERBB2 gene and are concomitantly overexpressed in HER2-positive breast cancer subgroups." (PMID 39482530, 2024). "From the CCLE and TCGA datasets, it was discovered that GRB7 and HER2 are co-amplified in OC, which is congruent with that in breast cancer." (PMID 39204147, 2024). "For the five identified potential oncomiRs, miR-193a-3p promoted tumor progression by targeting GRB7, ERK1/2, and FOXM1 signaling pathways and PTP1B in HER2-positive breast cancer cells." (PMID 37508580, 2023). "This study has demonstrated strong predictive ability of GRB7 and PGAP3 in combination for detecting HER2 amplified breast cancers." (PMID 37809181, 2023). "GRB7 overexpression facilitates the phosphorylation process of HER2 and AKT in breast cancer cells overexpressing HER2, morphologically alters the cells, and increases xenograft tumor growth in nude mice." (PMID 37945744, 2023). "We extracted DNA copy number and RNA expression data for HER2, GRB7, STARD3, and TOPA2 genes in 51 breast cancer cell lines." (PMID 36672312, 2023).
breast carcinoma (continued). "For instance, synthetic GRB7-binding peptides, which target to the SH2 domain of GRB7, inhibit the interaction between the GRB7 and ERBB family in breast cancer." (PMID 36686796, 2022). "Strikingly, ERBB2 and GRB7—chromosomally co-localized with ERBB2 and known to be frequently co-amplified with it in HER2-amplified breast cancer —are the two most significantly downregulated genes in the kinase+PTENloss group when compared to wildtype samples." (PMID 34344439, 2021). "Previous reports have identified co-amplification of GRB7, PNMT, and TCAP in HER2-positive breast cancer, specifically due to their location in the 17q12 region." (PMID 33087122, 2020). "In this study we confirmed the membrane accentuation of GRB7 protein expression in human breast cancer cell lines with HER-2 and GRB7 protein over-expression." (PMID 32595827, 2020). "The significance of GRB7 function is further supported by the laboratory findings that GRB7 over-expression facilitates HER-2 mediated signaling, breast cancer cell proliferation, and tumor formation in an animal model." (PMID 32595827, 2020). "GRB7, PNMT, and TCAP are expected to be amplified in HER2-positive breast cancers due to their location within the HER2 amplicon on the long arm of chromosome 17 (17q12)." (PMID 33087122, 2020). "Frequently affected genes by CNVs in Chinese breast cancer patients were ERBB2 (25%), MIEN1 (25%), GRB7 (24%), TRPS1 (6%), MYC (6%), ERLIN2 (6%), PLPP5 (6%), NSD3 (6%), FGFR1 (6%), and CCND1 (5%)." (PMID 33173047, 2020). "Knock down of GRB7 expression on the other hand, reduced the growth of HER-2 positive breast cancer cells in culture and as tumor xenografts in animal models." (PMID 32595827, 2020). "We began by applying the peptides to SKBR-3 (HER2+ve breast cancer cell line) and MDA-MB-231 (TNBC cell line) and examined the phosphorylation status of signaling molecules downstream of Grb7." (PMID 31627265, 2019). "G7-18NATE has been found to ablate the interaction between Grb7 and the ERBB family in a dose-dependent manner in breast cancer cells." (PMID 31083325, 2019). "In clinical trials, both GRB7 and ERBB2 have been indicated as two key genes in the 21 gene recurrence score assay to predict the recurrence of tamoxifen-treated breast cancer." (PMID 31083325, 2019). "On the other hand, knockdown of GRB7 expression has been indicated to attenuate ERBB2 and AKT phosphorylation in breast cancer cells, affecting ERBB2-mediated cancer growth in vivo." (PMID 31083325, 2019). "Cooverexpression or coamplification of Grb7 and the ERBB family has been clinically investigated in human breast cancers, cervical cancers, invasive Barrett’s carcinoma, advanced esophageal carcinoma, and gastric cancers." (PMID 31083325, 2019). "Currently, the use of the expression of both GRB7 and ERBB in the prediction of the recurrence of breast cancer has been validated in a clinical trial." (PMID 31083325, 2019). "Even though the fusion gene had been identified in breast cancer patients, the copy number amplicon (the one harboring the independent ERBB2 and GRB7 genes) had previously been reported in other cancer types, including gastric cancer." (PMID 29414922, 2018). "Marker Cluster 4 genes are enriched in HER2-positive breast cancers and includes ERBB2 (HER2), GRB7 and CEACAM6." (PMID 30279965, 2018). "We selected ERBB2, GRB7 and ONECUT2 for validation due to their importance in the biology of breast cancer, the magnitude of the change found in the RNA-seq data analysis and the consistency between the European and IA ancestry analyses." (PMID 28832682, 2017). "We used primers for the gene sequences of UBB, ESR1 (for luminal or ER/PR+ cancer cells), HER2 and GRB7 (for HER2+ cancer cells), EPCAM, KRT7, KRT8, KRT18, and KRT19, all of which have been commonly discussed for the purpose of breast cancer diagnosis." (PMID 28936247, 2015).
breast carcinoma (continued). "HER2-E breast cancers usually express high levels of HER2 and growth factor receptor-bound protein 7 (GRB7), the latter of which is also located in the HER2 amplicon on 17q21." (PMID 26561834, 2015). "We identified many known drivers of breast cancer and other types of cancer, in the female dataset (e.g. GATA3, CCNE1, GRB7, CDK4)." (PMID 24194916, 2013). "Cluster 2 (dark-blue) consisted of genes that are up-regulated in HER2+ breast cancer, including ERBB2, GRB7, STARD3 and PSMD3 that are located in the HER2 amplicon." (PMID 23945349, 2013). "Many known drivers of breast cancer, including GATA3, CCNE1, CDK4 and GRB7, as well as known drivers for other tumor types were identified among the FBC candidate drivers." (PMID 24194916, 2013). "Retroviral transgenesis was used to express constitutively active forms of Akt in the HER2+ breast cancer cell line SKBR3, and Grb7 in MCF7 cells." (PMID 20126311, 2010). "The GRB7 gene also co-amplifies with additional genes located within the ERBB2 amplicon such as CAB1, A39, C51 and MLN64 in gastric and breast cancers." (PMID 19424485, 2008). "The same effect is present in breast cancer cells overexpressing the circular RNA circCDYL2, which stabilizes GRB7 (growth factor receptor-bound protein 7), an adaptor protein involved in the signaling pathways mediated by HER2 (receptor tyrosine-protein kinase erbB-2) expression." (PMID 40283927, 2025). "circCDYL2 inhibits the binding of Pin1 with the GRB7 by interacting with GRB7, which leads to a decrease in the ubiquitination level of GRB7 and thereby stabilizes the expression of GRB7, resulting in the up-regulation of the GRB7 protein expression in HER2-positive breast cancer cells." (PMID 41169378, 2025). "The top differentially expressed genes (unadjusted P ≤ .001) were all upregulated and included KIFC1 (OMIM 603763), FAM83D (OMIM 618380), UBE2C (OMIM 605574), CLDN4 (OMIM 602909), GRB7 (OMIM 601522), and PKMYT1 (OMIM 602474), each of which have previously reported roles in breast cancer progression." (PMID 34714340, 2021). "The GRB7 gene is located in close proximity to the HER-2/erbB2 gene, forming the HER-2-amplicon core, and is commonly, though not always, co-amplified and overexpressed with HER-2 in human breast cancers." (PMID 32595827, 2020). "Moreover, EGF-induced Grb7-mediated Ras activation and ERK phosphorylation are required for breast cancer development." (PMID 31083325, 2019). "Indeed, both GRB7 and ERBB2 are key genes that predict the recurrence of breast cancer in clinical trials." (PMID 31083325, 2019). "Indeed, short hairpin RNA-mediated knockdown of GRB7 expression reduces cancer proliferation and anchorage-independent growth in ERBB2/Grb7-overexpressing breast cancers." (PMID 31083325, 2019). "In order to determine whether the G7-peptides could impact Grb7 mediated signaling pathways, we examined their effect on downstream ERK and AKT activation in fibronectin stimulated SKBR-3 and MDA-MB-231 breast cancer cell lines." (PMID 31627265, 2019). "The growth factor receptor-bound protein-7 (GRB7) gene is in close proximity to HER-2 on chromosome 17q11-12 and codes a signal transduction molecule shown to be an independent adverse marker in breast cancer." (PMID 24102037, 2013). "Thus, Grb7 and HER2, at least when amplified and overexpressed, appear act in concert to drive breast cancer formation." (PMID 20126311, 2010). "In addition, the genes TCAP, PSMD3, GRB7, and ERBB2 from the ERBB2 group are derived from the same well known breast cancer amplicon." (PMID 20158879, 2010). "Risk for death due to breast cancer was not statistically significantly associated with CD68, HER2, or GRB7 gene expression in patients treated or untreated with tamoxifen." (PMID 16737553, 2006).
breast carcinoma (continued). "Recently, it was proved that GRB7 was stabilized by circCDYL2 through preventing its ubiquitination degradation and enhanced its interaction with FAK, which thus sustained the activities of downstream AKT and ERK1/2 and contributed to trastuzumab resistance in HER2+ breast cancer patients." (PMID 39204147, 2024). "For example, circCDYL2 enhances the interaction between GRB7 and FAK by inhibiting the ubiquitination degradation of GRB7, thereby maintaining the activation of downstream AKT and ERK1/2 signaling pathways and leading to trastuzumab resistance in breast cancer." (PMID 37828589, 2023). "GRB7 could bind with RAS and promote its activation for the tumorigenicity of breast cancer." (PMID 33209198, 2020). "For example, STARD3, PNMT, CAB2, C17ORF37 and GRB7 show a significant correlation between amplification status and expression level, and STARD3, PNMT, CAB2, GRB7 and ZNFN1A3 could all be biologically relevant to breast cancer." (PMID 17117180, 2006). "In the analysis of two Her2-positive breast cancer markers, 571 co-regulated genes were identified in TRANSPATH and TRRUST combined, with no data available in either of the databases for GRB7." (PMID 36140706, 2022).
gastric cancer (17 papers, 2007 to 2025). A primary or metastatic malignant neoplasm involving the stomach. "Growth factor receptor bound protein 7 (GRB7) is reportedly upregulated in human gastric cancer (GC), which is closely associated with tumor progression and prognosis." (PMID 39360313, 2024). "In this study, GRB7 was observed to be frequently up-regulated in gastric cancer cells and tissues, and high GRB7 expression was associated with T Infiltrate and poor prognosis." (PMID 38129809, 2023). "Our in vitro functional assays further revealed that MyD88 partially reversed the promotion of cell proliferation and migration caused by GRB7 overexpression in gastric cancer." (PMID 38129809, 2023). "Our current research has found that elevated GRB7 expression is highly correlated with the advanced clinical stage or low survival rate of gastric cancer patients, indicating that GRB7 expression is expected to be a diagnostic and prognostic factor for gastric cancer." (PMID 36686796, 2022). "More importantly, GRB7 was highly expressed in the subtypes of gastric cancer in comparison to the para-carcinoma tissues." (PMID 38129809, 2023). "The results of functional experiments further revealed that GRB7 knockdown significantly inhibited the proliferative and migratory abilities of gastric cancer cells in vitro, as well as suppressed the tumor growth of gastric cancer in vivo." (PMID 38129809, 2023). "IHC staining were then employed to detect the expression pattern of GRB7 in gastric cancer tissues and para-carcinoma tissues." (PMID 38129809, 2023). "In this study, we aimed to investigate the potential role of GRB7 in the regulation of gastric cancer progression." (PMID 38129809, 2023). "Collectively, these results indicated that the GRB7 knockdown inhibited the progression of gastric cancer." (PMID 38129809, 2023). "The mRNA levels of GRB7 expression was also higher in gastric cancer cell lines AGS, MGC-803 and SGC-7901 compared to GES1 cells." (PMID 38129809, 2023). "When GRB7 was suppressed, it weakened the abilities of proliferation and migration in gastric cancer cells, increased the levels of apoptosis, as well as inhibited the tumor growth in vivo." (PMID 38129809, 2023). "Silencing MyD88 was observed to alleviate the malignant phenotypes promoted by GRB7 in gastric cancer cells." (PMID 38129809, 2023). "It was found that GRB7 expression was up-regulated in gastric cancer and negatively correlated with overall survival in these patients." (PMID 38129809, 2023). "In our study, GRB7 was significantly highly expressed in gastric cancer, and the prognosis of patients with high GRB7 expression was much worse than that of patients with low GRB7 expression." (PMID 38129809, 2023). "Our study discovered that GRB7 knockdown resulted in reduced cell proliferation and increased cell apoptosis in gastric cancer." (PMID 38129809, 2023). "GRB7 was up-regulated in gastric cancer tissues and cell lines, and its expression was inversely proportional to survival of gastric cancer patients." (PMID 38129809, 2023). "To further investigate the effects of GRB7 on gastric cancer tumorigenesis, we constructed a subcutaneous tumorigenesis model in vivo following GRB7 knockdown." (PMID 38129809, 2023). "Intriguingly, MyD88 depletion significantly weakened the promotive effect of GRB7 overexpression on malignant phenotypes of gastric cancer cells." (PMID 38129809, 2023). "The TCGA data revealed that MyD88 expression was positively correlated with the GRB7 expression in gastric cancer tumor samples." (PMID 38129809, 2023). "Altogether, these findings indicated that GRB7 knockdown significantly suppressed gastric cancer tumor growth." (PMID 38129809, 2023). "Based on this, the function roles of GRB7 in gastric cancer was investigated by a series of in vitro and in vivo experiments following GRB7 knockdown." (PMID 38129809, 2023).